CD4 (CD4 molecule)
Diseases named in the same sentence as CD4 in open-access papers (continued):
Sharing a sentence is not in itself a finding about the gene and the disease.
infection (continued). "At the early infection of 6 mpi, monkey infant RPn-8 had an unambiguously higher CD4+ T-cell counts of >2000 cells/ul, which was age-appropriate, and high viral loads compared to reports of other investigators, reflecting acute infection." (PMID 23840566, 2013). "Similiarly, SIVsmm infected SMs also exhibit lower frequency of infection of lymph node resident CD4+ TFH cells compared to SIVmac239 and SIVE543 infected RMs." (PMID 24009514, 2013). "In contrast, BrdU uptake by CD4+Foxp3− Teff cells at day 7 of infection was severely diminished in ICOS−/− mice." (PMID 23319295, 2013). "DC-SIGN allows for the capture of virus and its heightened transfer to CD4+ lymphocytes, termed trans-infection." (PMID 23874931, 2013). "Because nitric oxide (NO) has an important role in the suppression of CD4+ T cell proliferative responses in the acute phase of this model infection, we decided to measure the levels of iNOS mRNA in our liver samples by qtRT-PCR." (PMID 24312297, 2013). "In vitro analysis has indicated that CD8+ T cells can recognize gag-derived epitopes within the first 2 hours of SIV infection of primary CD4+ T cell lines and are capable of eliminating these cells early in the infection cycle." (PMID 23555209, 2013). "Significantly increased numbers of activated CD4+ T cells persisted in the lungs of immunized and RV infected mice on day 14 post-infection." (PMID 24086140, 2013). "One week after infection, PmpG-1-specific CD4 T cells expanded in iliac lymph nodes and spleen, but were barely detectable in other non-draining lymph nodes." (PMID 24204262, 2013). "As expected, intravenous infection with live Lm-Ova induced a high percentage of IFNγ-producing CD4+ T cells." (PMID 24068935, 2013). "DC-SIGN-mediated capture of HIV-1 and transmission of the DC-SIGN-captured virions to CD4+ T lymphocyte cells also represent an important pathway of infection for which CBAs have also been shown to act on." (PMID 23741304, 2013). "And once in the lymph nodes, the monocytes transfer invading antigens to dendritic cells to initiate the production of the CD4 T cells to lead the fight against the infection." (PMID 24220507, 2013). "For example, CD4+ T cells were shown in mouse infection models to play an important role in resistance to B. pseudomallei infection during the later stages of the acute infection." (PMID 23508691, 2013). "Diversity was independent of clinical markers (viral load, time from seroconversion, CD4 cell count) of infection." (PMID 23331949, 2013). "Analysis of recall responses during infection showed lower frequencies of IFN-γ producing CD4+ T cells in the spleen of Tc Muc treated mice, compared to untreated controls." (PMID 24204874, 2013). "If infection persists and the initiation of adaptive immunity occurs, the production of IL-17 is more commonly attributed TCRαβ CD4+RORγt+ Th17 cells." (PMID 23469071, 2013). "Our lab has examined the role of CD4+ Tregs, and demonstrated that Forkhead box P3 (FoxP3)+ CD4+ T-cells increase during the first 2 weeks of infection and plateau at about 18 days post infection (dpi)." (PMID 23680027, 2013). "In HIV-positive individuals, productively infected CD4+ T cells have a short half-life (1.6 days), and consequently a short time to spread the infection." (PMID 23899341, 2013). "Cytotoxic CD4+ T cell population appears at early stages of the infection concomitantly with high levels of IFN-γ and granzyme B expression." (PMID 24367519, 2013). "Chlamydia-specific CD4 T cells expanded rapidly and persisted as a stable memory pool for several months after infection." (PMID 24204262, 2013). "It is likely that, similar to HIV infection, the expansion in co-receptor usage in the replicating virus of the SIV+ CD4-low mangabeys enables the infection and depletion of a greater number of CD4+ T cells." (PMID 23825945, 2013).
infection (continued). "Immunity to infection with the large intestinal helminth parasite Trichuris muris is dependent upon CD4+ T cells that migrate to the large intestine." (PMID 23555902, 2013). "Human immunodeficiency virus type 1 (HIV-1) interactions with myeloid dendritic cells (DCs) can result in virus dissemination to CD4+ T cells via a trans infection pathway dependent on virion incorporation of the host cell derived glycosphingolipid (GSL), GM3." (PMID 23593001, 2013). "An analysis of the effect of vaccination on disease progression after infection showed weak evidence of lower viral load and higher CD4+ count in the vaccine group." (PMID 26344118, 2013). "These and other studies provided evidence that CD8+ and CD4+ Th1 cells are particularly important to the development of acquired immunity against experimental infection in mice." (PMID 23527169, 2013). "Here, we provide evidence that treatment of DCs with dectin-1/TLR2 and NOD2 ligands increases cis-infection of autologous CD4+ T cells by X4-using virus." (PMID 23844079, 2013). "We showed a massive spread of total HIV-DNA within all resting naive and memory CD4 subsets a month after infection, with only one viral cluster circulating throughout the blood and the rectal compartments." (PMID 23691172, 2013). "infection, suggesting that induced Chlamydia-specific Treg cells are also contained within the expanded CD4 pool." (PMID 24204262, 2013). "Intriguingly, ablation of IL-10 production and IL-10R1 expression did not lead to a marked increase in the frequencies or total numbers of effector CD4+T-bet+ T cells during infection." (PMID 23593003, 2013). "Similar to these kinetics, the peak proliferative capacity of CD4+ spleen T cells was observed at 4 weeks (67%) post-CDC1551-infection that declined to below 20% at 8 and 12 weeks." (PMID 23448601, 2013). "The same result was also obtained when data from patient 4 (who had similar infection frequencies in CD4+ T-cells from lymph node tissue and peripheral blood) were removed from the analysis." (PMID 23818847, 2013). "Taken together, these data indicate that the protection from infection observed in Itgb8 (CD11c-Cre) mice is driven by CD4+ T-cells, but independently of Foxp3+ Treg cells." (PMID 24098124, 2013). "In vitro, direct infection of naïve CD4 T-cells is less efficient than direct infection of memory CD4 T-cells." (PMID 23375003, 2013). "Comparable to DC-SIGN-expressing B cell lines, activated blood and tissue-derived B cells are highly efficient in mediating HIV-1 trans infection of CD4+ T cells." (PMID 24278768, 2013). "Upon infection Mtb primarily stimulates type 1 (Th1) cytokine reaction that is driven by the CD4+ T-cells." (PMID 24376464, 2013). "In both peripheral blood and lymph node we found that the infection frequency of memory CD4+ T-cells was substantially higher than that of naïve CD4+ T-cells." (PMID 23818847, 2013). "Infection with SIV resulted in a significant increase in the proportion of CD69-expressing CD4+ T cells, beginning in primary infection (Mann-Whitney test, p = 0.042)." (PMID 24348253, 2013). "The infected CD4+ T cells in the first days post infection (dpi) grow at a rate of 1.5 d−1 which is within the 1–2 d−1 range that has been reported." (PMID 24244151, 2013). "At 6 and 9 weeks after infection, the levels of PD-1 on CD4+T cells from TLR2−/− mice were significantly lower than those of B6 mice." (PMID 24376539, 2013). "Fading immunity in animal models is correlated with a reduction in CD4+ T cells, which leave the genital tract following resolution of infection." (PMID 23457650, 2013). "In the TB murine model CD4 T cell responses to Ag85B are therefore a prominent feature in early infection but there is a clear correlation between the down-regulation of fhpB and decreasing levels of T cell responses to this antigen." (PMID 24349004, 2013).
infection (continued). "Infection with a cell culture-adapted strain of virus results in an inapparent infection with low viral loads and stable CD4+ T cell numbers." (PMID 23372784, 2013). "Combining all the data for all the patients, we did, however, find statistical support for multiple infection in memory CD4+ T-cells isolated from lymph node tissue (p = 0.01)." (PMID 23818847, 2013). "In this study, we further confirmed the increased numbers and function of CD4+ and CD8+ T cells in mice with deficiency of TLR2 with the infection of Schistosoma japonicum." (PMID 24376539, 2013). "Both HTLV-1 and HTLV-2 are able to establish a persistent infection in CD4+ and CD8+ T cells but HTLV-1 establishes a more robust infection in T lymphocytes." (PMID 23966985, 2013). "As IL-4 mRNA levels are significantly lower in CD4+ T cells from WSX-1−/− mice than from WT mice on day 13 of infection our results suggest that the transition from Th1 to Th2 based immunity does not occur in WSX-1−/− mice during malaria infection." (PMID 23593003, 2013). "Our model results predict that RTS,S-induced protection from infection is dependent on both anti-CSP antibodies and CSP-specific CD4+ T cells, with antibodies playing a dominant role in preventing infection." (PMID 23613845, 2013). "In experimental infections, CD4+ lymphocytes are required for inducing immunity in ovine haemonchosis." (PMID 23509684, 2013). "Similar to the CD4+Foxp3+ Treg-cell population, ICOS−/− mice had significantly reduced numbers of CD4+Foxp3− Teff cells during infections with both H. polygyrus and S. mansoni." (PMID 23319295, 2013). "We next tested the impact of BAD-1 on the function of primary CD4+ T cells that respond to Blastomcyes in an antigen-specific manner and mediate immunity during infection." (PMID 23853587, 2013). "Previously, we generated recombinant Cc-CD4 and demonstrated Cc-CD4 was able to provide 22–56% protection from infection with HIV-1 pseudovirus representing clade B." (PMID 23840383, 2013). "Compared to WT mice, lower numbers of CD4+CD25+FoxP3+ Treg cells were detected in lungs of IL-10−/− mice at the 16th week post-infection." (PMID 24205424, 2013). "To gain insights into how CD4+ T cells contribute to the growth and development of schistosomes, we sought to delineate the interactions that occur between schistosomes and CD4+ T cells during the pre-patent stage of infection." (PMID 23556020, 2013). "In conclusion, we demonstrate that TLR-4 engagement in immature DC significantly up-regulates the intrinsic antiviral activity of BST-2/tetherin, during cis-infection of CD4+ T cells across the DC/T cell virological synapse." (PMID 23311681, 2013). "We next assessed the kinetics by which CD4+ T cells and inflammatory monocytes were recruited to the lamina propria during infection." (PMID 24130498, 2013). "We found that most of the DC-mediated transmission of R5-using virions toward CD4+ T cells is also due to a trans-infection mode." (PMID 23844079, 2013). "The proportion of CD4+IFN-γ+ T cells was increased significantly in B6.CCR7-/- mice as compared to B6.WT mice at day 14 after infection." (PMID 24205367, 2013). "A single day after infection half of the T lymphocyte culture was used to select CD4 expressing cells with magnetic beads (CD4 selected)." (PMID 23555263, 2013). "As expected, blockade of ICAM-1 with the mAb RM3A5 not only inhibited the formation of mDC-CD4+ T-cell conjugates, but also impaired the mDC-mediated trans-infection of HIV-1 to CD4+ T lymphocytes by 60% to 70% (p < 0.05)." (PMID 23590845, 2013). "The highest infection prevalence was at CD4+ T-cell counts less than 200 cells/μL and it was about five times higher than individuals having CD4+ T-cell counts greater than 500 cells/μL." (PMID 23991132, 2013). "The results of animal studies of genital chlamydial infection suggest that resolution of infection is dependent on a Type-1 CD4+ T-helper lymphocyte (Th1) response-mediated primarily through IFNγ." (PMID 23457650, 2013).
infection (continued). "A representative co-staining of IL-17 and IFN-γ within intestinal CD4+ T cells is shown in one IL-21-treated and one control RM at wks-2 (pre-infection), 4 (during the IL-21 treatment) and 23 p.i.." (PMID 23853592, 2013). "TIM-3 and PD-1 are coexpressed on both CD4+ and CD8+ T cells derived from individuals with chronic HIV or HCV infections and are associated with more severe CD8+ T-cell exhaustion." (PMID 23514593, 2013). "Knockout mice that did not receive WT cells began to die 10 days post-challenge, while all KO mice that received CD4+ T cells and all WT controls survived the acute phase of infection." (PMID 24130498, 2013). "Mechanistically, we find that enhanced TGFβ signalling in CD4+ T-cells during infection involves expression of the TGFβ-activating integrin αvβ8 by dendritic cells (DCs), which we have previously shown is highly expressed by a subset of DCs in the intestine." (PMID 24098124, 2013). "Infection with either clonal (Group 1) or diverse (Group 2) challenge viruses, resulted in a reduction in CD4+ lymphocytes and an increase in CD8+ lymphocytes." (PMID 23372784, 2013). "Of note, a positive effect of Nef on viral replication was observed in primary CD4+ T cells when the sources of infection were either cell-free viruses or infected lymphocytes co-cultivated with autologous targets (not shown)." (PMID 23899341, 2013). "In HIV-susceptible individuals, HIV exposure leads to penetration of the mucosal barrier and establishment of infection in a small focus of CD4+ target cells." (PMID 24257114, 2013). "Increasing the sample size by pooling the data from all of the patients did, however, reveal statistical support for multiple infection in memory CD4+ T-cells isolated from lymph node tissue." (PMID 23818847, 2013). "IL-8 is also involved in the recruitment of innate immune cells, neutrophils and CD4 positive T-cells to the site of infection." (PMID 23298379, 2013). "It is well accepted that antibodies and CD4+ T cells play critical roles in protection against blood-stage malaria that can be acquired during natural or experimental infection." (PMID 23527234, 2013). "A cytokine secretion assay 7 days after infection with L. major revealed only a very small number of IL-10-secreting CD4+ cells in the draining lymph nodes." (PMID 23825956, 2013). "By 21 weeks post-infection, CD4+ lymphocytes were depleted in both study groups, but most markedly in group 1." (PMID 23372784, 2013). "In this model, purified HPCs are infected shortly after isolation and latency is established within a few days, in a manner analogous to direct infection of resting CD4 T-cells." (PMID 23375003, 2013). "Previous studies have shown that sCD4 and some CD4 mimetic small molecules such as NBD-556 can activate infection in CD4-ve CCR5+ve cells." (PMID 24330857, 2013). "Since the 1990s we have known of the fascinating ability of a complex set of professional antigen presenting cells (APCs; dendritic cells, monocytes/macrophages, and B lymphocytes) to mediate HIV-1 trans infection of CD4+ T cells." (PMID 24278768, 2013). "Our results showed that a contact between mature DCs and resting CD4+ T cells is nonetheless a determining factor to establish a proper microenvironment for productive infection with X4 virions." (PMID 23844079, 2013). "To address this question, we studied 50 individuals recently infected with HIV-1, focusing on the frequency of HIV-specific T-cells, their potential to produce several cytokines, and the capacity of CD8+ T-cells to control infection of CD4+ T-cells ex vivo." (PMID 23555774, 2013). "In fact, a structurally modified scyllatoxin, a derived scorpion peptide, efficiently inhibited the binding of gp120 to CD4 in a competitive manner and thus suppressed the infection of CD4+ lymphocytes by human immunodeficiency viruses." (PMID 23843786, 2013).
infection (continued). "Infection with Listeria monocytogenes (either intravenous or enteric) induces clonal expansion of CD4 cells in a manner similar to CD8 T cells." (PMID 24171157, 2013). "This maintenance of suppression represents a difference with respect to the effect observed in CD4+ T-cells in that the inhibitory effect induced by pre-treatment with E2 is lost when E2 is present after infection." (PMID 23614015, 2013). "The infection frequency of naïve CD4+ T-cells was significantly lower (12-fold) than the infection frequency of memory CD4+ T-cells sorted from lymph node tissue (p = 0.01 and 0.01, method 1 and 2 respectively, paired t test)." (PMID 23818847, 2013). "Taken together, some proportion of the hepatic CD4+ T cells in the liver during the transition phase of the infection indeed acquired the capacity for producing IFN-γ, IL-13, and IL-4 simultaneously (“triple positive cells”)." (PMID 24358216, 2013). "Although CD4 T cells were shown to have direct effector function in some acute resolved infections, CD4 T cells are mainly thought to orchestrate other immune cells which then eradicate the infecting pathogens." (PMID 23717308, 2013). "CD137 – CD137L interactions have been shown to mediate the increase of myelopoiesis during infections by CD137+ CD4+ T cells accumulating in bone marrow and activating hematopoietic progenitor cells and their myeloid differentiation." (PMID 23945137, 2013). "TH cells are distinguished by cell surface expression of CD4 (i.e. CD4+ T cells) and promote effective immunity by secreting molecules that promote effective antibody and cellular responses upon infection." (PMID 24273551, 2013). "We also measured the effect of CD4 directed monoclonal Ab OKT4 by incubating TZM-bl cells with increasing concentrations of OKT4 before infection with pseudo-typed viruses." (PMID 23874931, 2013). "The transmembrane HIV-1 envelope protein gp41 has been shown to play critical roles in the viral mucosal transmission and infection of CD4+ cells." (PMID 23506331, 2013). "By lethal infection with PR/8 virus, the expression level of FasL was dramatically increased in all cell types, especially in CD4(+), CD11c(+), CD74(+) or NK1.1(+) cells (light green color compared with orange color)." (PMID 23408968, 2013). "In parallel with the low percentage of CCR5 expression, R5 HIV-1 fusion was rarely observed in the naïve subsets from both hNOJ mice and humans, confirming the CCR5-dependent infection of reconstituted CD4+ T cells by R5 HIV-1." (PMID 23301078, 2013). "In either case, the elimination of CD4+ T cells immediately after infection and before any viral genes are expressed should help prevent the establishment of latency." (PMID 23816179, 2013). "We now know that LC can mediate trans infection of CD4+ T cells with both R5 and X4 strains of HIV-1." (PMID 24278768, 2013). "Increased glucocorticoid (GC)levels are believed to be protective against the effects of acute stress during infection but resultin depletion of CD4+CD8+ thymocytes by apoptosis, driving to thymicatrophy." (PMID 24324845, 2013). "The efficiency of the APC-to-T cell trans infection pathway is dependent on the type and metabolic state of the CD4+ T cell." (PMID 24278768, 2013). "Consistent with the accumulation of LC3-II in HIV-infected CD4+ T cells, on day 5 post-infection, Beclin 1 protein level was higher in HIV-infected CD4+ T cells than in uninfected CD4+ T cells." (PMID 23658518, 2013). "Recently, treatment guidelines have changed and initiation of cART is recommended earlier in infection and at higher CD4+ T cell counts." (PMID 24098454, 2013). "In HIV-1BaL-infected cervico-vaginal tissues IL-7 25 ng/mL increased Bcl-2 expression in uninfected CD4+ T cells on average 2.0±0.3 fold on day 9 post infection (n = 4, p<0.05)." (PMID 23408885, 2013).